PDK1 (pyruvate dehydrogenase kinase 1)
Diseases named in the same sentence as PDK1 in open-access papers (continued):
Sharing a sentence is not in itself a finding about the gene and the disease.
melanoma (continued). "Moreover, studies have shown that c-Jun functions as a transcriptional regulator of PDK1 in melanoma and normal bronchial epithelial cells, promoting cell proliferation." (PMID 40482916, 2025). "Although downregulation of PDK1 was observed in shARNT cells, the correlation between PDK1 expression and melanoma progression remains unclear." (PMID 33446631, 2021). "In addition, shPDK1 cells were more resistant to apoptosis than control cells upon glucose deprivation, which reveals that depletion of the ARNT/PDK1 axis reduces the dependence of melanoma cells on glucose." (PMID 33446631, 2021). "Therefore, treatment with antioxidants to prevent chemotherapy-induced melanoma metastasis should be considered in patients using anticancer drugs that target cellular metabolism mediated by the ARNT/PDK1 pathway." (PMID 33446631, 2021). "As inhibition, silencing or gene ablation of PDK1 in experimental models have highlighted its suitability as a potential therapeutic target in breast, pancreatic cancers, and melanoma, understanding the precise mechanics of how PDK1 drives lung cancer development is of significant interest." (PMID 34789718, 2021). "Collectively, the results presented indicate that ACF, by inhibiting the transcriptional activity of HIF-1 in normoxia, negatively regulates PDK1 in melanoma cells, which could explain many of the effects observed after ACF treatment." (PMID 33396270, 2020). "Consequently, downregulation of PDK1 by acrifavine resulted in reduced glucose availability and suppression of the Warburg effect in melanoma cells." (PMID 33396270, 2020). "Furthermore, clinical data revealed that the expression of Ku80 and PDK-1 proteins were positively correlated and elevated in the tumor tissues of melanoma patients, and high expression of Ku80 predicted a poor prognosis in melanoma." (PMID 31023624, 2019). "As knockdown of Ku80 suppressed the expression of PDK1 and melanoma growth, we hypothesized that Ku80 regulated melanoma growth through PDK1." (PMID 31023624, 2019). "Collectively, our clinical data validated the oncogenic role of the Ku80/PDK1 pathway in melanoma." (PMID 31023624, 2019). "It is intriguing to test if HNI-38 can also inhibit the Ku80-regulated PDK1 expression, and synergize the oncostatic effect of melatonin, indicating that melatonin and Ku80 inhibitors in combination might be useful for melanoma treatment." (PMID 31023624, 2019). "Since dacarbazine has been shown to promote a relatively weak apoptotic response in melanoma we speculated that combining this cytotoxic insult with STAT3 silencing could be a good model to assess the contribution of the STAT3/PDK1 pathway on cell death." (PMID 30622697, 2019). "Additionally, we demonstrated that the melatonin exerted its antitumor effect via HIF1-α mediated Ku80/PDK1 pathway in part, and downregulation of Ku80 enhanced the antitumor effect of melatonin in melanoma." (PMID 31023624, 2019). "PDK1 inhibition has also received attention in SL melanoma drug screens, demonstrating synergy with PI3K pathway inhibition in PTEN wild‐type melanoma, and may provide a viable treatment option." (PMID 28097822, 2017). "PDK1 contributes to development of melanoma harboring the wild-type or knockout Pten genotype." (PMID 28430130, 2017). "Drug screening has, however, identified a possible SL interaction between PI3K/PDK1 which could be exploited to induce cell death in PTEN wild‐type melanoma." (PMID 28097822, 2017). "Ronai and colleagues have also pointed to an important role of PDK1 in melanoma." (PMID 26673621, 2016). "Notably, expression of PDK1 is sufficient to restore tumor growth after c-Jun knockdown in melanoma cells, suggesting that PDK1 is an important mediator of c-Jun oncogenic activities." (PMID 26684827, 2015). "Moreover, PDK1 depletion in melanoma tumors dramatically increased their sensitivity to vemurafenib in vivo by eliminating subpopulations of cells resistant to the drug." (PMID 24743024, 2014).
melanoma (continued). "Furthermore, depletion of PDK1 eradicated melanoma subpopulations resistant to RAF kinase inhibitors suggesting PDK1 might be a tractable therapeutic target for melanoma." (PMID 35409012, 2022). "In addition, the concurrence of ARNT and PDK1 expressions was observed in melanoma tissues." (PMID 33446631, 2021). "In addition, the combined treatment with BRAF and PDK1 inhibitors prevents melanoma growth." (PMID 33446631, 2021). "In accordance with our in vitro study, Ku80 overexpression dramatically promoted melanoma growth in tumor volume, size and weight, while Ku80 knockdown effectively suppressed melanoma growth, and such an inhibitory effect was reverted in part by PDK1 overexpression." (PMID 31023624, 2019). "In addition, PDK1 depletion, although present only in HLA-B,C-specific mAb B1.23.2-treated A375-M6 melanoma cells, together with an increase of PDP2, might have a role in triggering a cellular phenotype associated with an enhanced oxygen consumption rate." (PMID 31454998, 2019). "Indeed, PDK1 has been shown to control growth and progression of several tumors: breast, prostate, pancreatic, gastric, colorectal; ovarian, esophageal, gallbladder, acute myeloid leukemia and melanoma." (PMID 28287465, 2017). "For example, PDK1 promotes EMT and metastasis in nasopharyngeal carcinoma, increases CD47 expression to facilitate immune escape in melanoma, and drives proliferation and invasion in ovarian and hypopharyngeal cancers." (PMID 40971960, 2025). "Through literature mining, it was found that the four known melanoma-related proteins PIM1, MEK1, CDK2, and PDK1 can potentially be targets of the bioactive compounds of B. stenostachya." (PMID 40649898, 2025). "The pathway enrichment analysis revealed the four melanoma-related proteins PIM1, MEK1, CDK2, and PDK1 in several pathways including the pathways related to cancer." (PMID 40649898, 2025). "It is significant that the average docking scores for naringin-7-rhamnoglucoside and the melanoma-related proteins were as follows: PIM1 (−5.91897), MEK1 (−6.07004), CDK2 (−5.26133), and PDK1 (−6.29952)." (PMID 40649898, 2025). "In light of these findings, it becomes clear that melanoma cells exploit a diverse range of pathways which can be targeted by the bioactive compounds of B. stenostachya, particularly PIM1, MEK1, CDK2, and PDK1." (PMID 40649898, 2025). "In clinical tissue specimens, increased ARNT, pyruvate dehydrogenase kinase 1 (PDK1), and NAD(P)H quinine oxidoreductase-1 (NQO1) was observed in benign nevi, whereas lower expression was observed in melanoma." (PMID 33446631, 2021). "To address the effect of ACF on the expression levels of PDK1 and VEGF in melanoma cells, we then conducted knock-down experiments of HIF-1α." (PMID 33396270, 2020). "We show that PDK1 is a transcriptional target of STAT3, linking STAT3 pathway with AGC kinases activity in melanoma." (PMID 30622697, 2019). "Studies have shown that blocking the interaction between PDK1 and AKT can inhibit the growth and metastasis of melanoma." (PMID 31533855, 2019). "In SOX2-silenced control and acidic melanoma cells, we observed reduction of PDP2 and an appreciable increase of PDK1, suggesting an impaired mitochondrial OxPhos." (PMID 30466459, 2018). "Our findings demonstrate that Timp1 promotes cell survival with the participation of PDK1 and PKC in melanoma." (PMID 28430130, 2017). "Simultaneous inhibition of PDK1 and PI3K/mTOR or the proteasome exhibits synergism and has a higher impact on melanoma proliferation." (PMID 29064423, 2017). "Therapeutic efficacy of PDK1 inhibition by DCA has been showed for other tumors including glioma, melanoma." (PMID 28505181, 2017). "Using a melanoma progression model, we evaluated the impact of Timp1 and AKT silencing, as well as PI3K, PDK1, and protein kinase C (PKC) inhibitors on aggressiveness characteristics." (PMID 28430130, 2017).
melanoma (continued). "In a genetic mouse model of melanoma driven by melanocyte-specific expression of BrafV600E and inactivation of PTEN, the genetic inactivation of PDK1 delays the onset of the disease and almost completely abolishes metastases." (PMID 28287465, 2017). "Increased expression of PDK1 was observed in a large cohort of melanoma samples compared to nevi, and deletion of PDK1in a GEMM of melanoma BRAFV600E/PTEN-/- significantly delayed development of tumors and metastases." (PMID 24743024, 2014). "The highly supported results have shown that naringin-7-rhamnoglucoside from B. stenostachya could possibly target the genes involved in the progression of melanoma, specifically PIM1, MEK1, CDK2, and PDK1." (PMID 40649898, 2025). "In addition, inhibition of PDK1 by DCA, a PDK1 inhibitor, decreased the glycolytic status and cell proliferation of MDA-MB-435R (435R) cells, a human melanoma cell model." (PMID 39199957, 2024). "Interestingly, by inhibiting the HIF-1α/PDK1 axis, ACF modulates the metabolism of glucose in melanoma cells." (PMID 33396270, 2020). "Interestingly, PDK1 knockdown sensitizes BRAF-mutant melanoma to BRAF inhibitor treatment 132, suggesting the role of senescence PDK1-mediated drug resistance." (PMID 32483452, 2020). "We hypothesized that metabolic adaptation might be required, and indeed when melanoma cells were cultured in normoxic conditions for 3 weeks, the transcript levels of GLUT1, PDK1 and HK2 were markedly enhanced also in DMBC17 cells." (PMID 31461993, 2019). "Moreover, we showed that the binding of Ku80 at the PDK-1 promoter was HIF1-α dependent, and melatonin degraded HIF1-α in melanoma cells." (PMID 31023624, 2019). "Collectively, our study demonstrated that Ku80 promoted melanoma growth and regulated antitumor activity of melatonin by targeting HIF1-α dependent PDK-1 signaling pathway, suggesting that Ku80 may be a potential molecular target for melanoma treatment." (PMID 31023624, 2019). "Interestingly, in our melanoma progression model, Timp1 was shown to modulate the PI3K/PDK1 axis, since decreased Timp1 expression and PI3K inhibition attenuated PKD1 phosphorylation along with melanoma genesis." (PMID 28430130, 2017). "Interestingly, the inhibition of PDK1 with AZD7545 specifically suppressed growth of BRAF-mutant and BRAF inhibitor resistant melanoma cells." (PMID 28595656, 2017). "A study looking into metabolic changes in BRAF‐induced senescent cells did however find that depletion of pyruvate dehydrogenase kinase 1 (PDK1), a gatekeeper gene linking glycolysis to oxidative phosphorylation, selectively killed BRAFV600E‐mutant melanoma cells both in vivo and in vitro." (PMID 28097822, 2017). "We also showed that Timp1 modulates phosphorylation of PDK1 and PKC along melanoma progression." (PMID 28430130, 2017). "al. showing synergy between PI3K and PDK1 inhibitors in BRAF mutant melanomas." (PMID 26673621, 2016). "Therefore, the decrease in GLUT1 and PDK1 activity, two well-recognized HIF-1α-regulated genes, could have a major impact on the transport and usage of glucose in melanoma cells." (PMID 33396270, 2020). "Additionally, the expression level of PDP2 was upregulated without any detectable change in the expression of PDK1 in FO-1β2 melanoma cells incubated with the HLA-B,C-specific mAb B1.23.2." (PMID 31454998, 2019).
hepatocellular carcinoma (45 papers, 2012 to 2025). A malignant tumor that arises from hepatocytes. "In hepatocellular carcinoma, the epidermal growth factor receptor regulates YAP signaling through the PDK1 pathway to promote hepatocellular carcinoma cell growth." (PMID 37828220, 2023). "Activated Wnt signaling has been implicated in the enhancement of glycolytic activity in cancer cells, e.g., in nasopharyngeal carcinoma via the upregulation of pyruvate dehydrogenase kinase 1 or by increasing glucose uptake in hepatocellular carcinoma." (PMID 38132445, 2023). "LncRNA PDPK2P promotes AKT phosphorylation and inhibits the expression of caspase-3 by interacting with PDK1, and then inhibits the apoptotic pathway of hepatocellular carcinoma cells and promotes proliferation of tumor cells." (PMID 37313458, 2023). "For instance, circARNT2 facilitated DDP resistance in hepatocellular carcinoma cells through sequestering miR-155-5p to raise PDK1 expression." (PMID 36908025, 2023). "Blocking CDK1/PDK1/β-Catenin signaling would decrease stemness of cancer stem cells of hepatocellular carcinoma cells, and reverse sorafenib chemoresistance." (PMID 35078445, 2022). "Previous research revealed that the PDK1/AKT/Caspase 3 pathway is the mechanism through which lncRNA-PDPK2P promotes the development of hepatocellular carcinoma." (PMID 36267408, 2022). "PDK1 mRNA expression is elevated in human hepatocellular carcinoma, and Lin28 regulates PDK1 mainly via a post‐transcriptional mechanism, suggesting a novel rationale for targeting PDK1 for cancer therapy." (PMID 35656815, 2022). "Inhibition of the CDK1/PDK1/β-catenin signaling axis downregulates CSCs phenotype formation and enhances hepatocellular cancer sensitivity to sorafenib therapy." (PMID 34768921, 2021). "PDK1 is highly expressed in hepatocellular carcinoma (HCC) and enhances the resistance of HCC cells to radiotherapy by activating PI3K signaling; promoting HCC cell migration, invasion, and EMT; and enhancing cancer cell stemness." (PMID 39578715, 2024). "According to research, LncRNA-PDPK2P promotes hepatocellular carcinoma (HCC) progression via the PDK1/Akt/Casepase-3 signaling pathway, and PDPK2P expression can be used as a prognostic marker for HCC." (PMID 37064115, 2023). "Previous work has demonstrated that PDK1 is post-transcriptionally regulated by Lin28/Let-7g in hepatocellular carcinoma (HCC) cells." (PMID 29764469, 2018). "In fact, enhanced aerobic glycolysis has been observed in hepatocellular carcinomas overexpressing LIN28B, where LIN28B acts by targeting the metabolic enzyme PDH kinase 1 (PDK1)." (PMID 38338881, 2024). "In hepatocellular carcinoma, PGC1α suppresses aerobic glycolysis via suppressing WNT/β-catenin/PDK1 axis." (PMID 39220137, 2024). "Blocking CDK1/PDK1/β-Catenin signaling would inhibit proliferation and EMT of hepatocellular carcinoma cells." (PMID 35078445, 2022). "PDK1 inhibition by siRNAs in hepatocellular carcinoma (HCC).PDK1 inhibition by BX795 in HCC." (PMID 34900673, 2021). "Upregulated lncRNA XIST in hepatocellular carcinoma was found, in another study, to activate AKT pathway through positive regulation of PDK1 expression via inhibiting miR-139-5p." (PMID 31998636, 2019). "Notably, in hepatocellular carcinoma, GLIPR1 activates the PI3K/PDK1/ROCK1 signaling axis, thereby enhancing EMT, cellular motility, and resistance to 5-fluorouracil." (PMID 41208460, 2025). "As the previous study identified, CDK1 was overexpressed in hepatocellular carcinoma and was related to the development of tumor through the CDK1/PDK1/β-Catenin pathway, which could predict worse survival outcomes." (PMID 34187556, 2021). "Also, PDK1 (a HIF-1α target gene) drives PI3K/AKT/mTOR pathway activation, decreases BAX expression, and renders hepatocellular carcinoma cells resistant to irradiations." (PMID 34539584, 2021).
hepatocellular carcinoma (continued). "Hepatocellular carcinoma cell-derived EVs contain high levels of miR-21 that promotes CAF differentiation in recipient hepatocyte stellate cells by inhibiting PTEN and activating PDK1/AKT signaling." (PMID 32957712, 2020). "Similarly, in hepatocellular carcinoma (HCC), miR-21 derived from the tumor reduces PTEN levels, leading to the activation of the PDK1/AKT signaling pathway and an increase in the expression of VEGF, MMP2, MMP9, βFGF, and TGF-β in CAFs, thereby promoting angiogenesis." (PMID 37605155, 2023). "Several reports have shown that PDK1 can form complex with the Hippo components including MST1/2, SAV1, LATS1/2, and PDK1 recruited to the plasma membrane triggered by PI3K leads to dissociation of these complex and YAP activation in MCF-10A, HEK293T, and hepatocellular carcinoma cells." (PMID 34725466, 2021). "As a result of hypoxia-induced energy metabolism reprogramming, the augmented PDK1 expression in hypoxic tumors can drive the PI3K/Akt/mTOR signaling that promotes the EMT and formation of the radioresistant CSC-like phenotype, as it was shown for PDK1-overexpressing hepatocellular carcinoma." (PMID 33806538, 2021). "Hepatocellular carcinoma (HCC) cells secrete exosomes containing miRNA-21, directly targeting the PTEN gene and activating the PDK1/AKT signaling pathway, which promotes the transformation of normal hepatic stellate cells (HSCs) into CAFs with pro-cancer characteristics." (PMID 39534084, 2024). "Hepatocellular carcinoma (HCC) cell-derived exosomal miRNA-21 directly targeted PTEN (gene of phosphate and tension homology deleted on chromosome ten), leading to the activation of PDK1/AKT signalling in Hepatic stellate cells (HSCs), which are then transformed into CAFs." (PMID 38341827, 2024).